METAP2 (methionyl aminopeptidase 2)
Description:
Cotranslationally removes the N-terminal methionine from nascent proteins. The N-terminal methionine is often cleaved when the second residue in the primary sequence is small and uncharged (Met-Ala-, Cys, Gly, Pro, Ser, Thr, or Val). The catalytic activity of human METAP2 toward Met-Val peptides is consistently two orders of magnitude higher than that of METAP1, suggesting that it is responsible for processing proteins containing N-terminal Met-Val and Met-Thr sequences in vivo. Protects eukaryotic initiation factor EIF2S1 from translation-inhibiting phosphorylation by inhibitory kinases such as EIF2AK2/PKR and EIF2AK1/HCR. Plays a critical role in the regulation of protein synthesis.
Synonyms: p67; p67eIF2; MNPEP; MAP2
Tractability: Small molecule: a drug acting on it is in phase 2 or 3 trials; a structure with a bound ligand is known; a high-quality ligand is known; it has a binding pocket of medium quality; it belongs to a druggable protein family. Antibody: its Gene Ontology location is reachable by antibodies, with high confidence. PROTAC: it is named in the literature on targeted protein degradation; ubiquitination databases record sites on it; its protein half-life has been measured; a small molecule that binds it is known.
Target class: Protease; Enzyme; Metallo protease MG clan; Metallo protease; Metallo protease M24A subfamily
Chemical probes: BAY-277 (high quality), MetAP-2-IN-6, PD083324, PD084186, TP-004 (high quality)
Gene: Protein-coding gene on chromosome 12 (95,473,520 to 95,515,839, forward strand). Ensembl gene ENSG00000111142.
Subcellular location: Cytoplasm
Subcellular location (Human Protein Atlas): Cytosol; Plasma membrane
Pathways (Reactome):
Sensory Perception: Inactivation, recovery and regulation of the phototransduction cascade
Gene Ontology:
Molecular function: aminopeptidase activity; metalloexopeptidase activity; protein binding; RNA binding; initiator methionyl aminopeptidase activity; metal ion binding; metalloaminopeptidase activity
Biological process: protein processing; regulation of translational initiation; proteolysis
Cellular component: cytoplasm; cytosol
Genetic constraint (gnomAD): Loss-of-function variants: 13 observed, 27.42 expected, observed/expected ratio (o/e) 0.47, 90% interval 0.31 to 0.75. The upper end of that interval is the gene's LOEUF score, 0.75, which puts it in group 3 of 6, group 1 being the genes least tolerant of losing a copy. Missense variants: 222 observed, 361.84 expected, observed/expected ratio (o/e) 0.61, 90% interval 0.55 to 0.69. Synonymous variants: 132 observed, 129.81 expected, observed/expected ratio (o/e) 1.02, 90% interval 0.88 to 1.17.
Homologues: Orthologues: chimpanzee METAP2 (99% identical), macaque METAP2 (99% identical), dog METAP2 (98% identical), rabbit METAP2 (96% identical), guinea pig METAP2 (96% identical), pig METAP2 (96% identical), mouse Metap2 (95% identical), rat Metap2 (95% identical), rat Metap2-ps1 (94% identical), tropical clawed frog metap2 (84% identical), zebrafish metap2b (79% identical), Caenorhabditis elegans F53B6.5 (20% identical), and 1 more. Paralogues in human: PA2G4 (18% identical), XPNPEP2 (15% identical), XPNPEP1 (14% identical), PEPD (12% identical), XPNPEP3 (11% identical), METAP1D (11% identical), METAP1 (9% identical).
Diseases named in the same sentence as METAP2 in open-access papers:
METAP2 is named in the same sentence as 61 diseases in open-access papers, as found by Europe PMC text mining. Sharing a sentence is not in itself a finding about the gene and the disease. The quoted sentences say what the papers report.
breast carcinoma (6 papers, 2020 to 2023). "Knockdown of Metap1 or Metap2 alone already significantly impaired breast cancer cell growth in comparison to DMSO-only treated cells." (PMID 35673573, 2022). "In summary, knockdown of Metap1 or Metap2 sensitized murine and human breast cancer cells as well as human hepatocellular carcinoma and colorectal cancer to PI3K inhibition showing partly synergistic effects." (PMID 35673573, 2022). "Metap2-inhibitors are known to act tumor suppressive in various in vitro and in vivo cancer settings including breast carcinoma 62-64." (PMID 35673573, 2022). "In line with the known tumor promoting function of these proteases we demonstrated Usp7 and Metap2 to be important for murine and human breast cancer cell growth and discovered a role for Metap1 in this context." (PMID 35673573, 2022). "Synergistic effects on breast cancer cell growth were observed upon knockdown of Metap1 or Metap2 in combination with BKM EC10 and EC20 treatment in all three cell lines." (PMID 35673573, 2022). "In the present study we confirmed Metap2 as critical for breast cancer cells growth, in line with previous reports on its tumor-promoting function 62-64." (PMID 35673573, 2022). "Our data confirmed the known tumor promoting function of Usp7 and Metap2 in murine and human breast cancer cells, postulating a new importance of Metap1 for breast cancer cell growth." (PMID 35673573, 2022). "In murine breast cancer cells synergisms was also detected for combined Metap1 or Metap2 knockdown and BEZ treatment, despite for shMetap2-1." (PMID 35673573, 2022). "In human breast cancer cells METAP1 or METAP2 knockdown in combination with BEZ treatment reduced cell growth significantly better than knockdown alone but not significantly better than PI3K-inhibitor treatment alone, comparable with shRenilla control cells." (PMID 35673573, 2022). "In patient-derived breast cancer tissues, we found that MetAp2 is expressed and co-localized with lymphatic vessels." (PMID 32708166, 2020). "Histological samples of human breast cancers showed a high expression of MetAp2 and the co-localization of MetAp2 with lymphatic vasculature." (PMID 32708166, 2020). "A histological staining of tumors from human breast-cancer donors was performed in order to detect the level and the localization of MetAp2 and lymphatic capillaries." (PMID 32708166, 2020). "Additionally, Metap1, Metap2 or Usp7 knockdown sensitized PyMG-TA and PyB6-TA breast cancer cells to BKM treatment in comparison to cells with unaltered protease expression." (PMID 35673573, 2022). "This difference in susceptibility between breast cancer cells and non-cancerous cells was most prominent upon knockdown of Metap2 and Usp7." (PMID 35673573, 2022). "In addition, small but significant changes in PI3K pathway activation were observed upon knockdown of METAP1 or METAP2 in human breast cancer cells." (PMID 35673573, 2022). "Metap2 is known to act as tumor-promoting in different cancers including breast cancer." (PMID 36313646, 2022). "Importantly, we discovered an advantage for combining Metap1, Metap2 or Usp7 knockdown with PI3K inhibition to target breast cancer cells." (PMID 35673573, 2022). "In addition, we excluded involvement of several MAPK pathway related kinases in the combinatory effect of METAP1 or METAP2 knockdown with BKM treatment in human breast cancer cells." (PMID 35673573, 2022). "Because the synergistic effects might be due to a direct link of METAPs to PI3K signaling, we analyzed the activity of the PI3K pathway by means of the phosphorylation status of three players (Akt, mTOR, S6) upon METAP1 or METAP2 knockdown in human breast cancer cells." (PMID 35673573, 2022). "Specifically, knockdown of Metap1 or Metap2 impaired MTT viability and reduced competitive cell growth in murine breast cancer cells." (PMID 35673573, 2022).
breast carcinoma (continued). "Human tumor tissues were surgically resected and collected from breast cancer patients for the histological examination and detection of lymphatic endothelium (indicated by LYVE1 expression) as well as MetAp2 expression." (PMID 32708166, 2020). "Usp7, Metap1 and Metap2 are synthetic lethal partners of simultaneous protease/PI3K inhibition, which may refine future breast cancer therapy." (PMID 35673573, 2022). "In line with our screen data, Usp7, Metap1, Metap2, and MMP17 could be validated as depletion hits in vitro, whereby targeting reduced MTT viability and competitive breast cancer cell growth." (PMID 36313646, 2022). "In comparison to DMSO-only treated cells, knockdown of Metap1 or Metap2 stalled murine PyB6-TA cells in G1-phase and human MDAMB-TA cells in G2-phase, thus leading to an impaired cell cycle progression to S-phase in murine and human breast cancer cells." (PMID 35673573, 2022). "Next, we tested whether knockdown of Metap1 or Metap2 might provide synergistic effects to PI3K inhibition not only in murine breast cancer cells, but also in human MCF7-TA and MDAMB-TA cells representing luminal A-type and triple-negative breast cancers, respectively." (PMID 35673573, 2022). "Knockdown of Usp7, Metap1 or Metap2 impaired MTT viability to different extent, with both breast cancer cell lines being more sensitive than non-cancerous cells." (PMID 35673573, 2022).
Obesity (6 papers, 2015 to 2026). Accumulation of substantial excess body fat. "MetAP2 exhibits distinct expression patterns across various tissues and is implicated in metabolic processes related to obesity and T2DM." (PMID 39766279, 2024). "In clinical studies of obesity, beloranib, a MetAP2 inhibitor substantially increased weight loss along with improved glycemic control." (PMID 31264515, 2019). "In conclusion, inhibition of MetAP2, a regulatory element for angiogenesis and a target molecule for anti-angiogenic compounds are a promising approach to treating diabetes, obesity, and associated metabolic disorders." (PMID 31264515, 2019). "In preclinical models, METAP2 inhibitors induce weight loss and possess anti-tumor activity, but their effects on obesity-accelerated tumor growth are unknown." (PMID 41789003, 2026). "Although MetAP2 expression is relatively low in lean adipose tissue, obesity is associated with an increase in its expression, particularly in white adipose tissue, where it may contribute to lipid accumulation and reduced energy expenditure." (PMID 39766279, 2024). "Taken together, we have shown for the first time that a METAP2 inhibitor attenuates obesity-accelerated tumor growth." (PMID 41789003, 2026). "Here, we investigated the effects of SDX-7320, a novel polymer-conjugated METAP2 inhibitor, on obesity and obesity-accelerated tumor growth." (PMID 41789003, 2026). "By integrating structural, mechanistic, and pharmacological insights, this review aims to pave the way for the rational design of next-generation MetAP2 inhibitors, offering new hope for effective and safe treatments for obesity and T2DM." (PMID 39766279, 2024). "Although the therapeutic potential of MetAP2 inhibitors in T2DM and obesity has been recognized, direct links between MetAP2 inhibition and the modulation of these myristoylated proteins remain unproven." (PMID 39766279, 2024). "Despite its termination, ZGN-1061 demonstrated the potential of MetAP2 inhibition as a therapeutic strategy for obesity and T2DM." (PMID 39766279, 2024). "MetAP2 is a critical enzyme involved in metabolic regulation, making it a promising target for therapeutic intervention in obesity and T2DM." (PMID 39766279, 2024). "The anti-obesity efficacy of MetAP2 inhibitors has been demonstrated in animal models of obesity and in humans at low doses that do not affect angiogenesis." (PMID 35464063, 2022). "In pre-clinical models of obesity and diabetes, MetAP2 inhibitors have been shown to inhibit fat mass expansion and improve glycemic control, and reduce food intake in mice." (PMID 31264515, 2019). "The enzymemethionine aminopeptidase 2(MetAP2) promotes angiogenesis.MetAP2 inhibitors suppress angiogenesis and have potential anti-obesity effect." (PMID 31264515, 2019). "Beloranib (Zafgen®) is a novel injectable anti-obesity agent that can promote intracellular reduction in fat biosynthesis and fat oxidation and lipolysis by inhibition of methionine aminopeptidase-2 (MetAP2)." (PMID 26157708, 2015). "While MetAP2 inhibitors show promise in treating T2DM and obesity, and while Gαi, PKCε, and TRAM significantly impact these conditions, no direct studies have linked MetAP2 inhibition to the modulation of these proteins to alleviate T2DM or obesity." (PMID 39766279, 2024). "MetAP2 inhibitors have emerged as a significant class of compounds targeting a variety of diseases, including cancer, angiogenesis-related conditions, immune modulation, inflammation, and metabolic disorders such as obesity and T2DM." (PMID 39766279, 2024). "Although the clinical development of beloranib was halted due to safety concerns, particularly thromboembolic events, its mechanism, targeting MetAP2 to influence lipid metabolism and energy expenditure, highlights its potential as a therapeutic candidate for obesity and related metabolic disorders." (PMID 39766279, 2024).
Obesity (continued). "Understanding the tissue-specific roles of MetAP2 and its alterations in metabolic diseases offers insights into potential therapeutic strategies targeting this enzyme to alleviate obesity, improve glucose homeostasis, and mitigate complications associated with T2DM." (PMID 39766279, 2024). "Finally, the development and therapeutic potential of MetAP2 inhibitors are examined, with a particular focus on their mechanisms of action, clinical trial outcomes, and future prospects in treating obesity and T2DM." (PMID 39766279, 2024). "Building on this foundation, this review aims to focus on six representative MetAP2 inhibitors with preclinical or clinical research outcomes for type 2 diabetes and obesity, exploring their mechanisms of action, therapeutic potential, and results from these studies." (PMID 39766279, 2024). "Moreover, several MetAP2 inhibitors, such as fumagillin derivatives and newly developed reversible inhibitors, have demonstrated potential in preclinical and early clinical trials for obesity and T2DM." (PMID 39766279, 2024). "Inhibitors for human MetAP2 are well tolerated in patients at therapeutically relevant doses and have been developed for a variety of pharmaceutical applications, including the treatment of cancer, diabetes, and obesity, as well as the modulation of autoimmunity." (PMID 37511988, 2023). "This review provides a comprehensive analysis of MetAP2, including its structural characteristics, catalytic mechanism, and functional roles in the pathophysiology of T2DM and obesity." (PMID 39766279, 2024). "MetAP2 has been identified as a compelling target for therapeutic intervention in both T2DM and obesity." (PMID 39766279, 2024). "Collectively this proof of concept study supports a possible role for MetAP2 inhibitor BL6, as a putative anti-obesity therapeutic agent." (PMID 31264515, 2019). "However, in diet-induced obesity (DIO) models, significant alterations in MetAP2 expression are observed, reflecting its role in metabolic dysregulation." (PMID 39766279, 2024). "The exact mechanism behind the anti-obesity and anti-T2DM effects of MetAP2 remains unclear." (PMID 39766279, 2024). "Since discovering that human MetAP2, not human MetAP1, is the molecular target of TNP-470, a potent anti-angiogenesis inhibitor, MetAP2 has become a drug target for treating cancer, obesity, Prader-Willi Syndrome (PWS), and autoimmunity." (PMID 37511988, 2023). "The precise mechanism for the anti-obesity effect of MetAP2 inhibitors is not clear but the ability of MetAP2 to suppress activity of extracellular signal regulated kinases 1 and 2 (ERK1/2) represents one of the key mechanisms for the observed anti-obesity effect." (PMID 35464063, 2022).
microsporidiosis (4 papers, 2013 to 2025). A fungal infection caused by Microsporidia. "It was reported that microsporidian MetAP2 gene doesn't have any closer relationship to that of the other eukaryotes, making it a highly logical therapeutic target against microsporidiosis." (PMID 40129576, 2025). "The microsporidia contain only MetAP2 in their genome which makes microsporidia MetAP2 an essential target for designing therapeutic agents for microsporidiosis." (PMID 36674953, 2023). "The currently approved drugs for the treatment of microsporidiosis are albendazole and fumagillin, which target β-tubulin and MetAP2, respectively." (PMID 35356517, 2022). "Fumagillin has been intensely studied due to its potential in the treatment of amebiasis, microsporidiosis and most recently, for its anti-angiogenic activity as inhibitor of the human type 2 methionine aminopeptidase (MetAP2)." (PMID 24116213, 2013). "MetAP2 is a highly validated target for treatment of microsporidiosis." (PMID 40129576, 2025).
prostate carcinoma (4 papers, 2018 to 2025). A carcinoma that arises from epithelial cells of the prostate gland. "Nitroxoline showed anticancer activity in breast, bladder, pancreatic, and prostate cancer (as well as myeloma or gliomas) by activating cell apoptosis, arresting cell cycle, and suppressing angiogenesis through MetAP2 activity inhibition." (PMID 34830179, 2021). "When analyzing pathways associated with colorectal and prostate cancers, we observed that miRNAs targeting both NMT1/2 and MetAP2 genes also regulate the expression of key genes involved in these pathways, including AKT1, GSK3B, BRAF, MAPK and many others." (PMID 29579063, 2018). "Both in vitro and in vivo studies demonstrated that these AUTOTACs (e.g., PBA-1105, Anle138b-F105) effectively targets the androgen receptor (AR) in prostate cancer cells and methionine aminopeptidase 2 (MetAP2) in glioblastoma cells, showcasing its powerful degradation capabilities." (PMID 40008135, 2025).
colon cancer (3 papers, 2009 to 2021). "To find out if non-coding LIN28A mRNA regulates the expression of METAP2 through sponging miRNAs in colon cancer, we established Dicer knockdown cell lines and then evaluated the impact of over-expressed non-coding LIN28A mRNA on the expression of METAP2." (PMID 33665193, 2021). "Consistently, the expression of LIN28A decreased upon knockdown of METAP2 in colon cancer cells, whereas this phenomenon was also abolished upon knockdown of Dicer." (PMID 33665193, 2021). "As expected, we showed that both miRNAs significantly targeted the expression of LIN28A and METAP2 in two colon cancer cell lines." (PMID 33665193, 2021). "Additionally, we noticed that, contrary to non-coding LIN28A and METAP2, let-7 and miR-181 inhibited the migration and invasion of colon cancer cells." (PMID 33665193, 2021). "We further determined whether the roles of METAP2 in colon cancer are consistent with those of the non-coding LIN28A mRNA by assessing the effects of METAP2 on the migration and invasion of colon cancer cells." (PMID 33665193, 2021). "Moreover, we detected the mRNA expression of LIN28A and METAP2 by using RT-PCR and revealed that the two were positively correlated with each other in 46 colon cancer tissues (r = 0.533)." (PMID 33665193, 2021). "From our above observations it is evident that MetAP2 may serve as a novel target for the treatment of colon cancer." (PMID 19703310, 2009).